MLANA (melan-A)
Diseases named in the same sentence as MLANA in open-access papers (continued):
Sharing a sentence is not in itself a finding about the gene and the disease.
melanoma (continued). "The combination of three antibodies, anti-Melan A, -S100β and -Gp100 detected all melanoma cell lines well and showed negligible interaction with PBMCs." (PMID 30735560, 2019). "To relate results obtained using cell lines to clinical data, we isolated melanoma cells from patients’ biopsies (identified by Melan-A staining) and then treated them with foretinib, gefitinib, and lapatinib separately or in combinations." (PMID 31649529, 2019). "To determine the potency of ApoEV-HM-loaded moDC to prime naïve T cells, we used the MART-1 (/Melan-A) as a melanoma-specific antigen." (PMID 31466401, 2019). "Melan-A is another immunohistochemical marker that was found to be positive in a small percentage of HMB-45-negative melanomas." (PMID 30635729, 2019). "Consistent with the results showing changes in MLANA transcript levels, treatment of MITF-Mhigh melanoma cells with vemurafenib or trametinib for 44 h resulted in increased percentages of Melan-A-positive cells." (PMID 31354817, 2019). "By contrast, the occult micrometastasis contained only few SOX10+ Melan A- melanoma cells which were scattered within a dense infiltrate of T cells, including a prominent population of CD103+ CD8+ T cells resembling tissue-resident memory T (TRM) cells." (PMID 31885869, 2019). "Immunohistochemical studies showed extensive staining by HMB-45 and focal immunoreactivity for Melan-A and S100, confirming melanoma and expression of these two antigens in the new lesion." (PMID 31703593, 2019). "According to immunohistochemical analysis, the tumor cells were positive for melanoma-specific markers Melan A and HMB45." (PMID 30782194, 2019). "This was followed by the positive selection for either PanCK+ cells (breast cancer CTCs) or CD146+/Melan-A+ cells (melanoma CTCs)." (PMID 31003475, 2019). "Melanoma tumors are often enriched in melanoma-reactive TILs of both high and low avidity, whereby Melan-A-specific T cells are frequently detectable among the melanoma-reactive TILs in HLA-A2 positive patients." (PMID 31555299, 2019). "Though melanomas express tumor antigens such as melan-A (also known as MART-1, melanoma antigen recognized by T cells), which can adequately signal an adaptive anti-tumor immune response, this can be effectively suppressed by the tumor cells." (PMID 31426515, 2019). "The Melan-A positive staining in the spleen demonstrated the implantation of melanoma cells; co-injected HSteCs were also detected using αSMA." (PMID 31344830, 2019). "In melanoma patients vaccinated with a mixture of Melan-A peptide combined with Montanide and CpG, the ability to elicit anti-Melan A CD8+ T cells expressing VLA-1, a surrogate marker of TRM, was correlated with better survival." (PMID 30100906, 2018). "Melan-A labelling was performed in order to confirm the diagnosis of melanoma as well as to identify the location of the melanoma cells in the tissue." (PMID 30060843, 2018). "We developed a clinical grade procedure for the selection and amplification of polyclonal CD8 T cells, specific for two shared and widely expressed melanoma antigens: Melan-A and MELOE-1." (PMID 30214446, 2018). "For this, we first confirmed that all melanocytes and melanoma cells were stained with the phenotypic melanocye marker Melan-A." (PMID 30719424, 2018). "At the antigen specific T cell level, a recent study from a phase I clinical trial enrolling melanoma patients vaccinated subcutaneously with a melanoma antigen (Melan-A), analyzed the homing receptors characterizing Melan-A-specific CD8 T cells." (PMID 30258445, 2018). "As expected, less than 50% of amelanotic melanomas in this study were positive for Melan A, confirming the poor sensitivity of this marker." (PMID 30314485, 2018). "In 89 cases where tumour cells were identified by melan-A labelling, 100% of tumour cells were positive for nBAP1 expression, including eight uveal tract and 29 oral mucosal melanomas." (PMID 30060843, 2018).
melanoma (continued). "In this study of 90 melanoma cases, the 89 cases that were melan-A positive labelled with 100% positivity for nBAP1 protein expression within the tumour cells." (PMID 30060843, 2018). "Melanoma antigens, including Melan-A, tyrosinase, and gp-100, were strongly expressed at the RNA level." (PMID 29750176, 2018). "Recently, the expression of the melanocyte-specific markers MITF, MLANA and TYR has been associated with a highly proliferative melanoma cell phenotype that metastasizes to multiple organs." (PMID 30053879, 2018). "The well-known and often used melanoma tumor-associated antigen (TAA), MART-1/Melan-A is an immunogenic self-antigen expressed in both normal and malignant melanocytes." (PMID 30022005, 2018). "We chose the top and bottom 11% (n = 50) of melanomas in terms of MLANA expression and identified the differentially expressed genes considering our 44 differentially expressed genes." (PMID 29454361, 2018). "The lesion was immunohistochemically stained strongly for melanoma-specific antigens melan-A, S-100, and HMB45." (PMID 29197361, 2017). "They then concluded that MART-1/ MLANA and ABCB5 are helpful in following high-risk melanoma patients confirming that MCAM/MUC18/CD146 expression is associated with poorer outcome in stage IV disease." (PMID 28280601, 2017). "Melan-A has also been identified as a melanocytic differentiation marker, which is recognized as an antigen on melanoma cells, by cytotoxic T-lymphocytes." (PMID 29019940, 2017). "The T cell clones of this study were derived from melanoma patients, and from their polyclonal T cell populations specific for HLA-A2/Melan-A (hereafter called polyclonal or “total” population)." (PMID 28287160, 2017). "On Melan-A specific CD8+ T cells isolated from melanoma patients, LAG-3 is highly co-expressed with PD-1 and TIM-3." (PMID 28404974, 2017). "Markers included MCSP, a melanoma cell surface specific marker, together with a mixture of internal melanocytic markers, gp100 (glycoprotein 100), S100, and MLANA, hereafter called “MEL” immunostaining." (PMID 28978038, 2017). "Quantification of MYSM1+Melan-A+ double-positive cells in normal skin, melanocytic nevi, and melanoma confirmed the increase in MYSM1 expression during step-wise transformation of normal melanocytes to malignant melanoma cells." (PMID 28978033, 2017). "Melanoma origin of these cells was verified by the positive detection of MART-1/Melan-A, a melanocyte-specific marker." (PMID 28759024, 2017). "The upregulation of MITF correlated with increased expression of its target genes TYR and MLANA, which is in line with previous observations of increased melanoma differentiation antigen expression on treatment, and indicates that MITF is functional." (PMID 26977879, 2016). "In support, our data demonstrate that re-expression of p97/VCP in Melan-A/MART-126-35 CTL-resistant melanoma cells completely restored immune recognition by Melan-A/MART-126-35 CTL." (PMID 27143649, 2016). "The results of the present study indicate that making this kind of distinction using standard melanoma-associated markers would be very difficult because MM127 cells cannot be identified using S100, Melan-A, HMB-45, MITF or tyrosinase." (PMID 27087056, 2016). ", melanoma (Melan-A, human melanoma black-45, and tyrosinase), and carcinoma (cytokeratin) markers are typically absent." (PMID 27429816, 2016). "IL PV-10 led to tumor regression in both an injected and an uninjected bystander lesion, shown by IHC staining for the melanoma antigen Melan-A/MART-1 (melA) in the biopsy specimens." (PMID 27177220, 2016). "Immunofluorescence analysis of the metastatic lesion revealed that FN was expressed in both stromal and melanoma (Melan-A–positive) cells, whereas POSTN and COL-I were localized only in stromal cells." (PMID 26083413, 2015). "MTFs stained strongly for markers specific for melanocyte lineage, including MLANA, and for cell surface markers often found in melanomas, such as ALCAM." (PMID 26267609, 2015).
melanoma (continued). "We have previously established melanocytic markers like MLANA to distinguish between the proliferative and invasive phenotype on a cohort of primary melanoma cell cultures." (PMID 25885555, 2015). "In all primary melanomas, we routinely observed many apparent MTFs, which stained for macrophage (pan- and M2-polarization) markers, as well as for melanocyte-specific (MLANA) and epithelial (EpCAM and pan-KRT) markers." (PMID 26267609, 2015). "The melanoma-origin of the detected cells in culture and in samples from patients was confirmed via co-staining for anti-Melan-A, thus distinguishing melanoma cells (DAPI+/GFP+/Melan A+) from the surrounding WBCs (DAPI+ /GFP- /Melan A-)." (PMID 25807549, 2015). "Because of their expression of HMB-45 and/or melan-A, PEComas are frequently confused with both conventional melanoma and clear cell sarcoma." (PMID 26268324, 2015). "MTFs were readily identifiable in primary melanomas, with strong staining for melanocyte (MLANA and ALCAM), macrophage (CD204, CD206), and epithelial (pan-KRT, EpCAM) markers." (PMID 26267609, 2015). "We therefore examined the expression of melanoma-specific differentiation genes including Melan-A (MLANA), Tyrosinase (TYR) and Tyrosinase-related protein 1 (TYRP1) by quantitative PCR." (PMID 24406338, 2014). "A tissue biopsy showed a poorly differentiated malignant tumour with morphological and immunohistochemical features consistent with melanoma (S-100 protein, Melan A/MART-1 and HMB45/Gp100 all positive)." (PMID 24679002, 2014). "We compare the ability of NY-ESO-1 or Melan-A specific T cell clones to recognize and kill melanoma cell lines, which were phenotypically either E-like or switched to M-like following incubation with TGFβ." (PMID 25566505, 2014). "Typically, melanoma cells produced uniform or punctate cytoplasmic staining pattern for Melan-A and both cytoplasmic and nuclear distribution for S100B." (PMID 24811334, 2014). "In contrast, Melan-A specific T cells were significantly more effective at killing E-like melanoma cells prior to induction of EMT." (PMID 25566505, 2014). "Previous studies have also shown that the activation of AKT suppressed melanin production in human melanoma G631 and murine melanocyte Melan-A cells." (PMID 25045707, 2014). "Based on our previous studies, we selected four E-like melanoma cell lines, which were HLA-A*0201+, and which were also positive for expression of either Melan-A, or NY-ESO-1, or both." (PMID 25566505, 2014). "CMCs were identified by immunocytochemistry using Melan-A or S100B as melanoma markers and enumerated using automated microscopy image analyses." (PMID 24811334, 2014). "The melanomas all express varying levels of differentiation antigens Melan-A/MART-1, gp100 and TRP-2, as well as the MHC Class I antigen (as evidenced by staining with W6/32 antibody) that is required for T cell recognition of the tumor cells." (PMID 25503774, 2014). "Using the Melan-A/MART-1 promoter EGFP system in the melanoma cell line MU89, we showed that cells treated with 4 separate Hsp90 inhibitors (17-AAG, 17-AEP, CCT018159, and PU-H71) significantly enhanced the fluorescent reporter signal as early as 2 days." (PMID 25503774, 2014). "After vaccination of melanoma patients with HLA-A2-restricted Melan-A peptide, monitoring with HLA-DQ6-restricted Melan-A peptide multimers revealed a downshift in specific Tregs with increased effector T cell responses." (PMID 24904570, 2014). "IFN-β, but not IFN-α, was shown to increase mRNA and protein expression of melanocytic tumor-associated antigens (Melan-A/MART-1, gp100, MAGE-A1) in 15 melanoma cell lines, inducing susceptibility to lysis by cytotoxic T lymphocytes." (PMID 24516470, 2014). "We previously reported FOXP3 expression in human melanomas by demonstration of co-staining of FOXP3 with the melanoma cell surface antigen Melan-A." (PMID 24406338, 2014).
melanoma (continued). "T cells, which recognized the HLA-A*0201 restricted epitope 157–165 from NY-ESO-1 or 26–35 from Melan-A were incubated with melanoma cell lines expressing their respective target antigen, at a 1:1 effector:target ratio." (PMID 25566505, 2014). "S-100 is highly sensitive while HMB-45 and melan-A are highly specific in diagnosing malignant melanoma." (PMID 25093125, 2014). "Results first show that meloe promoter (from P-1565 to P-415) is as active as Melan-A promoter in melanoma cells." (PMID 24086527, 2013). "Melan-A, a marker that recognizes normal melanocytes as well as antigens present on melanomas, was detected in the present study in some epithelial cells." (PMID 23356913, 2013). "When looking at the distribution of melanoma and non-melanoma ratio of nuclei or the total area of Melan-A positive tissue area, similar levels were observed in both cohorts." (PMID 23690928, 2013). "Among the many melanoma antigens that have been identified so far, we chose to target the melanocytic differentiation antigen Melan-A/MART-1 and the melanoma overexpressed antigen MELOE-1." (PMID 24194775, 2013). "A melanoma vaccination protocol based on an MHCI-restricted Melan-A peptide significantly decreased the frequency of Melan-A-specific Treg, in association with an improved and more diverse Th1 response." (PMID 23986759, 2013). "In the present work, we provide a detailed description of the whole GMP process of sorting and amplification of clinical grade T cells specific for the melanoma antigens Melan-A and MELOE-1." (PMID 24194775, 2013). "Histologic analysis of tumors with H&E, and immunohistochemical staining with anti-Ki67 Ab (a proliferation marker) or anti-Melan-A Ab (a melanoma marker) revealed similar expression of these proteins by the three cancer cell line-derived tumors." (PMID 23626777, 2013). "Images of the deconvolved H-CHANNEL of the melanoma and non-melanoma, for these cell nuclei using the Melan-A binary masks also show distinctive granularity features." (PMID 23690928, 2013). "We compared 2 groups of melanoma patients for changes in absolute MLANA levels vs. MIF levels based on time following surgery." (PMID 22829910, 2012). "50% of melanoma patients have tumour-infiltrating lymphocytes (TILs) recognising tyrosinase and Melan A, indicating that these antigens are important in the natural melanoma immunosurveillance." (PMID 22506061, 2012). "Neoplastic cells of the ocular neoplasm expressed Melan A and vimentin, similarly to those observed in domestic felines’ melanomas." (PMID 23009723, 2012). "EM revealed a marked loss of pigmentation in the melanoma MALME-3M cells treated with albumin-associated lipids, in accordance with the downregulation of MLANA gene expression." (PMID 23961369, 2012). "Substantial increases in MLANA transcripts were observed in ∼ one-third of melanoma patients, accompanied by increases in MIF." (PMID 22829910, 2012). "These authors described MLANA-RNA-expressing cells which appeared consistent with melanoma cells, as well as putative macrophage-melanoma hybrids." (PMID 22829910, 2012). "Of these, the shared antigens, such as tyrosinase and melan-A in the case of melanoma, are well-defined and have broad specificity for melanoma patients." (PMID 22438914, 2012). "So far, despite S100 immunostaining with the 97–100% sensitivity and 75–87% specificity, additional higher specificity markers such as HMB-45 (69–93%), and MART-1/Melan-A (75–92%) have been used to assist in the differential diagnosis for melanoma." (PMID 23028750, 2012). "Our results indicate that ∼1/3 of melanoma patients (nearly all of them early stage) have significantly elevated levels of MLANA and MIF marker RNAs compared with healthy volunteers, and similar results have been reported in a number of other studies." (PMID 22829910, 2012).
melanoma (continued). "More recently, the impact of the peptide dose on CD8 T-cell avidity has been investigated in melanoma patients vaccinated with different doses of Melan-A/MART-1 peptide." (PMID 23227083, 2012). "In the framework of our melanoma program, some patients were vaccinated simultaneously with three different short peptides derived from Melan-A, NY-ESO-1 and MAGE-A10." (PMID 22347406, 2012). "Thirdly certain AIRE single nucleotide polymorphisms associated with reduced AIRE stability are significantly more frequent in healthy patients than in melanoma patients and so are Melan A-specific T cells, again implying protective effects of AIRE deficiency." (PMID 22506061, 2012). "In melanoma, the Melan-A antigen fulfils these requirements and we recently reported the efficiency of a Melan-A modified SLP, to cross-prime human tumour-reactive T cells." (PMID 23284752, 2012). "In contrast, areas with epithelioid single cells expressed vimentin and Melan A, indicating melanoma cells." (PMID 23009723, 2012). "Western blotting analysis showed that the NVs and exosomes contained similar levels of melanoma antigens, such as tyrosinase and melan-A." (PMID 22438914, 2012). "Immunostaining with three melanocytic markers S-100, HMB-45 and Melan-A in melanoma cells was cytoplasmic, but nuclear staining was also noted with S-100." (PMID 22143732, 2012). "IFN-beta is an additional stimulus to TAAs expression in melanoma, including Melan-A/MART-1, gp100, and MAGE-A1, permitting an improve of immune response to melanoma cells." (PMID 22190975, 2011). "For example, on the basis of the successful use of gp100, MART-1/Melan-A, and tyrosinase in melanoma preclinical models, several clinical trials were conducted or are still ongoing." (PMID 24212974, 2011). "The HMW-MAAnegative fraction consisted mainly of non-melanoma cells (“normal” stromal cells), since there were hardly any cells expressing a melanocytic marker Melan A in this fraction." (PMID 20505780, 2010). "Immunohistochemical detection of nodal metastasis has also been incorporated and must include at least one melanoma-associated marker (e.g., HMB45, Melan-A, and Mart-1) unless diagnostic cellular morphology is present." (PMID 20936153, 2010). "We conducted an in-depth characterization of 210 T-cell receptor beta chain (TRB) clonotypes derived from T cells of HLA-A2+ melanoma patients displaying cytotoxic activity against natural and A27L-modified Melan-A peptides." (PMID 19317896, 2009). "Melan-A is one of the melanoma antigens most frequently recognized by peripheral and tumor-infiltrating lymphocytes in HLA-A2+ melanoma patients." (PMID 19317896, 2009). "On the contrary, TRBV28 chain is significantly more represented in HLA-A2+/Melan-A-specific T-cell clones obtained from melanoma patients and controls." (PMID 19317896, 2009). "Collectively, the present analysis demonstrated that in melanoma patients there is a biased T-cell response to Melan-A, which is characterized by TR clonotypes using preferentially TRBV28 and TRBJ1-5 segments and containing a 12-amino acid-long CDR3." (PMID 19317896, 2009). "The amino acid composition of TRB hypervariable regions of Melan-A-specific CTL from melanoma patients were subsequently analyzed in detail." (PMID 19317896, 2009). "TRB sequences of Melan-A-specific clonotypes obtained from melanoma patients were highly heterogeneous, but displayed a preferential usage of few TRBV and TRBJ segments." (PMID 19317896, 2009). "Further, Qu Spez-educated DC stimulated CD4+T cells in a allogeneic mixed lymphocyte reaction and activated melanoma antigen Melan-A/MART-1-specific M77-80 CD8+T cells as evidenced by increased secretion of TNF-α and IFNγ." (PMID 18533025, 2008). "HBL and D10 HLA-A*0201+ melanoma cells expressing Melan-A/MART-1 and gp100 differentiation TAA cultured in 2D or 3D were used to stimulate IFN-γ production by previously characterised specific CTL clones." (PMID 17342088, 2007).